TLR4 (toll like receptor 4)
Diseases named in the same sentence as TLR4 in open-access papers (continued):
Sharing a sentence is not in itself a finding about the gene and the disease.
autoimmune disease (continued). "Anti-inflammatory effects in autoimmune diseases and neurodegeneration also appeared to suppress the inflammatory activity of TLR4-NF-κB/ NLRP3 inflammasome pathway and provided novel mechanistic insights for the potential therapeutic for cervical cancer." (PMID 29423077, 2018). "Toll-like receptor 4 (TLR4) is one of the key players in the development of many autoimmune diseases." (PMID 28446897, 2017). "In this paper, we aim to review the functions of TLR4 in B cell immune response and antibody production in autoimmune disease APS and try to find a new way for the prevention and treatment of APS." (PMID 27868072, 2016). "We investigated a panel of genes previously shown to be linked with GD as well as genes associated with other autoimmune diseases (e.g., IRF5 and TLR4)." (PMID 27014188, 2016). "As a contributor to TLR2/TLR4 pathway, it has been attributed a pivotal function in the pathogenesis of autoimmune diseases." (PMID 26442097, 2015). "Our findings raise a caveat against targeting TLR4 for therapy of organ specific autoimmune disease precisely because of its pleiotropic effects." (PMID 24586934, 2014). "Similar to Tlr2, Tlr4 enhances the severity of autoimmune disorders (EAE) in mice, where it promotes IFN-γ and IL-17 production by γδ T cells and IL-2 secretion and proliferation of NKT." (PMID 25147831, 2014). "Taken together we provide further evidence that both immunosuppressive treatment – regularly used in the treatment of e.g. in autoimmune disease – or anti-TLR4 treatment impair endogenous pain control mechanisms." (PMID 24499354, 2014). "The results presented here have uncovered an essential function of TLR4 in the induction of the chemokine CXCL1/KC in an organ-specific autoimmune disease." (PMID 24586934, 2014). "TLR4 is a major pharmaceutical target in septic shock, inflammatory and autoimmune diseases, allergy and cancer." (PMID 22196451, 2012). "In view of previously published work suggesting a role for MIF in the expression level of TLR4, these results suggest an association between TLR4 and MIF in patients with autoimmune disease." (PMID 20596538, 2010). "In this study, we investigated the effect of TLR-4 and TLR-9 gene polymorphisms on the organ-specific autoimmune disease GD in a Taiwanese population." (PMID 21050493, 2010). "Resistin is implicated in cardiovascular, metabolic, and autoimmune diseases, as it affects molecular pathways associated with inflammation, including the activation of NFKB1 nuclear factor kappa B (NF-kB) by Toll-like receptor 4 (TLR4)." (PMID 39335642, 2024). "Expression of SNHG16, TLR4 and TRAF6 and cell death processes were examined in lung tissues and peripheral blood (PB) leukocytes from AH patients associated with SLE and other autoimmune diseases, and in the lungs and spleen from a pristane-induced C57BL/6 mouse AH model." (PMID 37700342, 2023). "TLR2/TLR4 have emerged as targets for treating a wide array of autoimmune disorders." (PMID 36969199, 2023). "However, when TLR4 is overactivated or its negative regulatory system is obstructed, TLR4 can induce endotoxic shock, autoimmune disease, and even cytokine storm where the immune system attacks the host." (PMID 34746034, 2021). "Recent human studies demonstrated that TLR4 plays a pivotal role in autoimmune diseases, including DLE, and therefore might represent a potential target for future immunotherapeutic approaches." (PMID 33917661, 2021). "Inhibition of TLR4 is a therapeutic candidate in autoimmune diseases including IIM." (PMID 32164729, 2020). "Similarly, IRAK4 inhibitors, ND-2158 and ND-2110 attenuated TNFα production from TLR4/9-stimulated human PBMCs and autoimmune disease in collagen-induced arthritis and gout murine models." (PMID 31354711, 2019). "This confirms the thesis that TLR-2 and TLR-4 may be involved in the development of autoimmune diseases." (PMID 31554206, 2019).
autoimmune disease (continued). "The PBD carries a significant segment, the PBM, that could serve as a decoy to prevent or dissociate TIRAP from the membrane in order to control dysregulated and overexpressed TLR2/TLR4/TLR7/TLR9-dependent autoimmune diseases." (PMID 29434596, 2018). "A group of studies have demonstrated that TLR4 plays an important role in autoimmune diseases." (PMID 28446897, 2017). "TLR4 is one of the most extensively studied TLRs involved in autoimmune diseases." (PMID 28424490, 2017). "Thus, we proposed that TLR4 can promote B cells to develop into Bregs to secrete IL-10, thus inhibiting the development of inflammation and autoimmune diseases." (PMID 27868072, 2016). "Effects of ligands of TLR2 or TLR4 on different cells in autoimmune diseases." (PMID 27199979, 2016). "Therefore, we believe, based on our data that treatment should not only target TLR7/8 and TLR9, but also should target the effect of TLR4 signaling on lupus pathogenesis, and gender differences in other autoimmune diseases." (PMID 25485543, 2014). "However, while the role of Tlr4 in triggering autoimmune diseases is well established, its influence in cytokine production is still debated." (PMID 25147831, 2014). "Because CSP-AU1 had potent TLR4-dependent immunomodulatory effects via MD-2, we hypothesized that this polysaccharide might have a clinically beneficial effect on autoimmune diseases." (PMID 23806004, 2013). "The hypothesis that TLR4 signaling is involved in autoimmune diseases has prompted research into TLR4 inhibition." (PMID 24137239, 2013). "SRMA itself seems to be maintained by multiple alterations of the immune system resulting in an autoimmune disease, TLRs, such as TLR4 and TLR9, might act as receptors maintaining the inflammation." (PMID 23016675, 2012). "Therefore, TLR4 is attracting more attention in the field of autoimmune diseases." (PMID 35292659, 2022). "Thus, the plasma level of sTREM-1 may serve as a reliable biomarker for TLR-4-mediated innate immune activation in infectious as well as sterile inflammatory disorders, including autoimmune diseases." (PMID 30616644, 2019). "Previous studies have shown that TLR4 may play a critical role in various autoimmune diseases." (PMID 28446897, 2017). "However, excessive activation of TLR4 can lead to autoimmune disorders and inflammatory diseases." (PMID 26198237, 2015). "In line with this, direct TLR4 stimulation in CD4 T lymphocytes has been shown to promote T helper 17 responses and to aggravate the evolution of autoimmune diseases, indicating that the observed decrease in IL-17 production may indeed contribute to the suppressed arthritis in TLR4 defective mice." (PMID 21858160, 2011). "TLR4, which is a PAMP receptor, has been demonstrated as the trigger of inflammation in several microbial infections, autoimmune diseases, and cancerous events." (PMID 39670742, 2025). "TLRs, such as TLR2, TLR4, TLR7, and TLR9, are involved in this process, and their dysfunction or overexpression in immune cells plays a pivotal role in the pathogenesis of autoimmune diseases." (PMID 38732254, 2024). "TLR2, TLR4, TLR7, and TLR9 recognize PAMPs from infectious agents and DAMPs from tissue damage, contributing uniquely to the pathogenesis of specific autoimmune diseases." (PMID 38732254, 2024). "The binding of extracellular HMGB1 to Toll-like receptors (TLRs), such as TLR2 and TLR4 transforms HMGB1 into a pro-inflammatory cytokine, contributing to the occurrence and development of autoimmune diseases." (PMID 37667233, 2023). "For example, in macrophages, TIM-3 is responsible for regulating the response to toll-like receptor 2 (TLR2) and toll-like receptor 4 (TLR4) stimulation, thus inhibiting the release of proinflammatory cytokines in autoimmune diseases." (PMID 37345111, 2023).
autoimmune disease (continued). "In particular, inappropriate signaling by TLR4, TLR7, and TLR9 induces hyper-activation of the immune system and contributes to numerous pathological conditions like inflammation and autoimmune diseases." (PMID 34025679, 2021). "Numerous studies suggest that TLR4-, TLR7- and TLR9-mediated abnormal activation of the macrophages, DCs and B cells contributes to the pathogenesis of inflammation and autoimmune diseases." (PMID 34025679, 2021). "Since PKM2 positively regulates the activation of the TLR4/TLR7/TLR9 pathways under in vitro conditions, the effect of PKM2 in relieving the TLR-mediated inflammation and autoimmune diseases was assessed." (PMID 34025679, 2021). "Thus, considering our results and those of others, although the evidence remains limited, a suitable drug design, such as C70PLY4, targeting TLR4 activity might provide an opportunity to effectively treat the majority of chronic inflammatory and autoimmune diseases in the future." (PMID 32397494, 2020). "Specifically, TLR4 expressed in dendritic cells and macrophages contributes to autoimmune disorder systemic lupus erythematosus via TH1 polarization, which can be suppressed by conditional knockout of TLR4 and MyD88 on macrophages and DCs." (PMID 32512831, 2020). "High levels of TLR2 and TLR4 expression on myeloid DCs and TLRs TLR7 and TLR9 present in pDCs may have specific functions in autoimmune disease in which molecular mimicry or autoantibodies to essential nucleic acids are a potential underlying mechanism for autoimmune disease onset." (PMID 28396662, 2017). "We also observed a substantial increase in the TLR4 mRNA transcript expression in RA patients in comparison to the patients with SLE, another autoimmune disorder." (PMID 28424490, 2017). "With the help of TLR4, B cells secrete some cytokines to regulate innate and adaptive immunity in APS autoimmune diseases." (PMID 27868072, 2016). "Secondly, we also examined these phenotypes in the context of the autoimmune disease model of multiple sclerosis, where pretreatment of murine MSCs with TLR3 and TLR4 agonists generates distinct and opposing immunomodulatory effects on EAE." (PMID 27724984, 2016). "Indeed, chronic stimulation of the innate immune system via TLR4 leads to the induction of immunosuppression, and several plant polysaccharide with immunomodulatory activities were recently found to have therapeutic effects in several autoimmune disease models, including EAE." (PMID 23806004, 2013). "TLR4 specifically recognizes the LPS of gram-negative bacteria and is involved in various autoimmune diseases." (PMID 36749400, 2023). "Toll-like receptor 4 (TLR4) and one of its endogenous ligands myeloid-related protein 8 (MRP8 or S100A8), especially expressed in macrophages, play an important role in diabetic nephropathy and autoimmune disorders." (PMID 32080297, 2020). "Interactions between MIF, TLR4 and TCR/CD3 are complex and understanding their nature could have translational impacts on immunomodulatory approaches for treating inflammatory and autoimmune diseases." (PMID 31253838, 2019). "The present study extends our understanding of TIRAP’s membrane association, which could be helpful in designing peptide decoys to block TLR2-, TLR4-, TLR7-, and TLR9-mediated autoimmune diseases." (PMID 29434596, 2018). "Clinically, JAK inhibitors (e.g., tofacitinib) already approved for autoimmune diseases show promise in preclinical models by reducing IL-6/STAT3-driven EMT, while TLR4 or NLRP3 inhibitors could blunt the initial DAMP-induced inflammatory cascade that seeds EMT." (PMID 41019090, 2025). "It has been demonstrated in another autoimmune disease that Hsp70 overly activates dendritic cells at the beginning phase of the disease and induces excessive TNF-α and Interleukin-17 (IL-17) release from these dendritic cells, with TLR4/nuclear factor-kappa B (NF-κB) pathway participation." (PMID 37108693, 2023).
Alzheimer disease (117 papers, 2008 to 2026). A progressive, neurodegenerative disease characterized by loss of function and death of nerve cells in several areas of the brain leading to loss of cognitive function such as memory and language. "Elevated TLR4 expression and associated overactive microglia were observed within a transgenic mouse model of Alzheimer’s Disease (AD) leading to cognitive impairment." (PMID 35782423, 2022). "TLR4 also participates in the development/progression of neurodegenerative disorders associated with Alzheimer's disease (AD), Parkinson's disease (PD), multiple sclerosis, and amyotrophic lateral sclerosis (ALS)." (PMID 33057840, 2021). "TLR4 received attention when an Italian study found that the TLR4 polymorphism is responsible for late-onset of Alzheimer’s disease in the Italian population." (PMID 34827372, 2021). "The TLR4 +896A/G coding variant (rs4986790) is underrepresented in patients with myocardial infarction, Alzheimer's disease or prostate cancer, whereas it is more frequently found in centenarians in Italian and Canadian cohorts." (PMID 32391019, 2020). "Activation of TLR4 leads to pro-inflammatory responses causing neuronal injury and secretion of neurotoxic compounds in Alzheimer’s disease (AD) and Parkinson’s disease (PD)." (PMID 32784362, 2020). "A report regarding the relationship between the TLR4 gene polymorphisms and late-onset Alzheimer’s disease (LOAD) showed that participants with AA genotype of rs1927907 had a significantly increased risk of LOAD." (PMID 27652106, 2016). "TLR4 variants have also been associated with Alzheimer’s disease." (PMID 38002250, 2023). "The activation of TLR4 can clear amyloid beta (Aβ) accumulation at the initial stage; however, chronic long-term activation causes Aβ deposition in the brain, which causes or aggravates Alzheimer's disease." (PMID 36523959, 2022). "TLR4 polymorphisms have been associated with an increased risk of infections, and such conditions as tonsillitis, ulcerative colitis, Crohn’s disease, age-related macular degeneration, and Alzheimer’s disease." (PMID 32957083, 2020). "Similarly, TLR4 activation is associated with development of Alzheimer’s disease." (PMID 33799689, 2021). "In conclusion, our study demonstrates that SLAMF8 and NINJ2 are key drivers of neuroinflammation and oxidative stress in Alzheimer’s disease by activating the TLR4/NF-κB pathway." (PMID 40394132, 2025). "Activation of TLR4 in astrocytes accelerates Aβ production and contributes to the pathological processes of Alzheimer’s disease." (PMID 40870800, 2025). "In various animal models, such as ischemia/reperfusion, Alzheimer’s disease, and autoimmune illnesses, TLR4 controls inflammation and tissue damage." (PMID 40973956, 2025). "Parallel mechanisms have been reported in Alzheimer's disease and intestinal inflammation models via TLR4/NF-κB/inflammasome inhibition." (PMID 40726812, 2025). "For example, TLR4 and TLR212, as well IRAK413 have been implicated in the development of Alzheimer’s disease, while TLR2, TLR4, and TLR9 have been suggested to have a dominant role in Parkinson’s disease." (PMID 39014006, 2024). "In a mouse model of Alzheimer’s disease, pain is attenuated because microglia lack expression of TLR4." (PMID 37349313, 2023). "For example, targeting the TLR4/NFκB pathway downregulates the proinflammatory response in both a mouse model of Alzheimer’s disease and traumatic brain injury." (PMID 35639336, 2023). "Remarkably, when administered to mice with an Alzheimer’s disease model, Pls were found to significantly reduce TLR4 endocytosis, providing further evidence for the anti-inflammatory effects of 1-O-alkyl-glycerols through an additional molecular mechanism." (PMID 37367676, 2023). "Hyperactivation of monocytes and macrophages in response to TLR2 and TLR4 stimulation in ‘mild cognitive impairment’ patients contributes to the progression of Alzheimer’s disease." (PMID 36140198, 2022).
Alzheimer disease (continued). "TLR4 activation has been demonstrated to be responsible for chronic inflammation present in Alzheimer's disease, epilepsy, Parkinson's disease, and other nervous system diseases." (PMID 36523959, 2022). "TLR4 agonists were suggested to have a therapeutic potential for Alzheimer’s disease by stimulating the immune system to clear amyloid β." (PMID 36678520, 2022). "It is worth mentioning that TLR4 regulates inflammation and tissue injury in different animal models, for example, ischemia/reperfusion, Alzheimer’s disease, and autoimmune disorders." (PMID 34630092, 2021). "TLR4 plays a key role in various diseases, such as inflammatory bowel disease, sepsis, Alzheimer’s disease, and cancers; it can induce prolonged and excessive inflammatory signals, resulting in serious damage to various tissues." (PMID 33799689, 2021). "This antibody impeded HMGB1-mediated TLR4-dependent biological effects in vitro and exerted beneficial therapeutic effects in a preclinical model of Alzheimer ́s disease." (PMID 34943830, 2021). "TLR4 has been found involved in the deposition and scavenging of amyloid-beta and regulation of neuroinflammation in Alzheimer’s disease." (PMID 35153741, 2021). "In fact, TLR4-dependent microglial activation has been observed in various neurodegenerative diseases like Alzheimer’s disease (AD) and Parkinson disease (PD)." (PMID 34063947, 2021). "TLR4, an important member of the TLRs family, is involved in various neurodegenerative diseases, including Alzheimer's disease (AD), Parkinson's disease (PD), Huntington's disease (HD), amyotrophic lateral sclerosis (ALS) and so on." (PMID 32432571, 2020). "TLR4-dependent activation of microglia is crucial in degenerative and traumatic CNS diseases including Parkinson’ s disease, Alzheimer’s disease, and brain/spinal cord injury." (PMID 32019561, 2020). "Aging and amyloid β oligomers, the neurotoxin involved in Alzheimer’s disease, enhance TLR4 expression as well as LPS-induced Ca2+ responses and neuron cell death in rat hippocampal neurons aged in vitro." (PMID 28143556, 2017). "Toll-like receptor 4 (TLR4) signaling in the brain mediates autoimmune responses and induces neuroinflammation that results in neurodegenerative diseases, such as Alzheimer’s disease (AD)." (PMID 27093924, 2016). "In this case, activation of microglia through TLR4 appears to be neuroprotective in Alzheimer’s disease." (PMID 23388509, 2013). "Numerous studies have demonstrated TLR4-dependent activation of microglia in neurodegenerative diseases and trauma in the central nervous system (CNS), such as Alzheimer’s disease (AD) and Parkinson’ s disease (PD), as well as brain injury induced by ethanol." (PMID 23388509, 2013). "In Alzheimer’s disease, activated microglia expressing galectin-3 bind to TLR4 (Toll-like receptor 4), MerTK, and TREM2 (triggering receptor expressed on myeloid cells 2), which facilitates amyloid-beta clearance and promotes inflammatory responses associated with the disease." (PMID 40429840, 2025). "To gain deeper insights into the regulatory mechanisms of SLAMF8 in Alzheimer’s disease (AD), we assessed the expression levels of Toll-like receptor 4 (TLR4), phosphorylated p65 (phospho-p65), total p65, phosphorylated IκBα (phospho-IκBα), and total IκBα across different experimental groups." (PMID 40394132, 2025). "For instance, in Alzheimer‘s disease (AD), fibrillar amyloid-β (Aβ) deposits engage microglial pattern recognition receptors (e.g., TLR4), leading to NLRP3 inflammasome activation, which exacerbates tau hyperphosphorylation and cognitive deficits in murine models." (PMID 40137280, 2025). "Such insights could facilitate the development of novel interventions targeting TLR4-mediated neuroinflammatory pathways in diseases such as Alzheimer’s disease, multiple sclerosis, and Parkinson’s disease." (PMID 40872491, 2025).